NF1 (neurofibromin 1)
Diseases named in the same sentence as NF1 in open-access papers (continued):
Sharing a sentence is not in itself a finding about the gene and the disease.
Proteus syndrome (1 paper, 2011). Proteus syndrome (PS) is a very rare and complex hamartomatous overgrowth disorder characterized by progressive overgrowth of the skeleton, skin, adipose, and central nervous systems. "Finally, Stedman's Medical Dictionary provides two definitions of “elephant man's disease”, one being that it is a synonym for Proteus syndrome and the other that it is a colloquial way of referring to NF1." (PMID 21347399, 2011).
psychological distress (1 paper, 2017). "Neurofibromatosis 1 (NF1) is an inherited, multi-system, tumour suppressor disorder with variable complications that cause psychological distress and social isolation." (PMID 28193237, 2017).
rectal carcinoma (1 paper, 2017). A malignant epithelial neoplasm that arises from the rectum and invades through the muscularis mucosa into the submucosa. "In summary we presented a rare case of NF1 patient associated with multiple GISTs and rectal carcinoma." (PMID 28835241, 2017). "In our case, the NF1 patient had multiple GISTs and rectal carcinoma." (PMID 28835241, 2017). "Negative regulation of RAS protein by neurofibromin 1 may affect the carcinogenesis of the rectal carcinoma." (PMID 28835241, 2017).
sarcoidosis (1 paper, 2025). Sarcoidosis is a multisystemic disorder of unknown cause characterized by the formation of immune granulomas in involved organs. "We present an interesting case of severe PH in a postmenopausal woman with NF1 since 1973, and sarcoidosis diagnosed in 2009." (PMID 41523545, 2025).
sarcomatoid carcinoma (1 paper, 2018). A malignant epithelial neoplasm characterized by the presence of spindle cells and anaplastic morphologic features.
sebaceous carcinomas (1 paper, 2021). "Tetzlaff and colleagues found two patients with NF1 gene mutations in a collective of 27 sebaceous carcinomas." (PMID 34065301, 2021).
sebaceous tumor (1 paper, 2021). "Patient 4 had a solid-cystic sebaceous tumor, with a NF1 mutation." (PMID 34065301, 2021).
sensory ataxia (1 paper, 2022). Any ataxia in which the causes of the disease is a perturbation of the sensory system, leading to its dysfunction. "This case with NF-1 shows asymmetric sensory ataxia of subacute progression." (PMID 36397418, 2022).
separation anxiety disorder (1 paper, 2025). An anxiety disorder characterized by recurrent excessive distress due to fear of separation from the home or from major attachment figures; the distress is developmentally inappropriate and causes impairment in social, academic, or other areas of functioning. "Parent-reported scores showed a significant association between NF1 and separation anxiety disorder." (PMID 41210128, 2025).
small cell carcinoma (1 paper, 2013). A neuroendocrine carcinoma composed of small malignant cells which are often said to resemble "oat cells" under the microscope. "Moreover, in one study, it has been reported that the loss of heterozygosity in chromosome 17p—but not in 17q—was detected in a patient with small cell carcinoma with NF-1." (PMID 23533906, 2013).
Social anxiety disorder (1 paper, 2025). "Social anxiety disorder was absent among children with NF1 yet was present in 14.9% of those with NSSD." (PMID 40725498, 2025).
spinal cord astrocytoma (1 paper, 2025). A low or high grade astrocytoma that arises in the spinal cord.
spinal cord injury (1 paper, 2022). Penetrating and non-penetrating injuries to the spinal cord resulting from traumatic external forces (e.g., WOUNDS, GUNSHOT; WHIPLASH INJURIES; etc.). "In the present study, lentiviral vectors were used to knock out NF-1, Ricotr (the core member of mTORC2) or NF-1+Ricotr in neural stem cells in vitro, and the NF-1, Ricotr or NF-1+Ricotr knockout neural stem cells were transplanted at the lesion site in a rat model of spinal cord injury (SCI)." (PMID 36241865, 2022).
Spinal meningoceles (1 paper, 2014). "Spinal meningoceles, which are observed in 60-85% of patients with NF-1 can cause headache, coughing, dyspnea, sometimes with back pain with or without motor and sensory symptoms and should be treated surgically when possible." (PMID 25852768, 2014).
status epilepticus (1 paper, 2024). Status epilepticus is defined as a continuous seizure lasting more than 30 min, or two or more seizures without full recovery of consciousness between any of them. "This ranged from stage 1 through stage 7 of behaviours, with two mice (one Nf1+/− + LPS and one WT + Saline) developing very severe seizures and dying from status epilepticus during testing." (PMID 38685949, 2024).
Stillbirth (1 paper, 2023). Death of the fetus in utero after at least 22 weeks of gestation. "The proportions of stillbirths (PR 2.83; 95% CI 1.63 to 4.93) and spontaneous abortions (PR 1.40; 95% CI 1.09 to 1.79) were increased in women with NF1." (PMID 37095468, 2023).
Superior Vena Cava Syndrome (1 paper, 2021). A condition that occurs when the obstruction of the thin-walled SUPERIOR VENA CAVA interrupts blood flow from the head, upper extremities, and thorax to the RIGHT ATRIUM. "Here, we present a rare case of NF1 in a 3-year-old boy admitted with respiratory distress and superior vena cava syndrome." (PMID 34782848, 2021).
thrombophilia (1 paper, 2026). A condition characterized by an abnormally high level of thrombi. "Whole-exome sequencing detected exclusively a pathogenic variant in the NF1 gene, with no other pathogenic/likely pathogenic variants or thrombophilia-associated polymorphisms being found." (PMID 41515658, 2026).
transitional cell carcinoma (1 paper, 2021). A malignant neoplasm arising from the transitional epithelium, usually affecting the urinary bladder, ureter, or renal pelvis. "While there is documented evidence to suggest that the NF1 gene may play a role in the pathogenesis of transitional cell carcinoma (TCC) of the bladder, there is a paucity of documented cases of TCC in patients with NF1." (PMID 34745780, 2021).
trauma (1 paper, 2025). "Lack of tumors in males from the control Prss56Cre, Nf1+/+ cohort, and in mutant males and females housed individually, suggested their development promoted by skin trauma or inflammation." (PMID 41223283, 2025).
trichorhinophalangeal syndrome (1 paper, 2014). "For example, she had no cutaneous tumors or facial features of trichorhinophalangeal syndrome, so the rare variants reported in NF1 and TRPS1 were likely benign variants or possibly false positives." (PMID 24954083, 2014).
Uterine leiomyoma (1 paper, 2009). The presence of a leiomyoma of the uterus. "At first glance, the association of uterine leiomyoma and NF1 may seem coincidental, as the first condition is frequent in the general population." (PMID 19946501, 2009). "We report here the unusual case of a 47-year-old woman with NF1 who presented menorrhagias and a hard, tender pelvic mass composed of uterine leiomyomas." (PMID 19946501, 2009). "Moreover, the association of uterine leiomyoma and NF1 may not be fortuitous." (PMID 19946501, 2009).
ventricular septal defect (1 paper, 2025). The presence of a defect (opening) in the septum that separates the two ventricles of the heart. "NF1 and GLI3 are both linked with multiple forms of CHDs, including atrial and ventricular septal defects, which are common forms of CHDs that are also associated with CHD genes such as NKX2–5 and TBX5." (PMID 40857331, 2025).
vitreous hemorrhage (1 paper, 2024). Blood extravasation in the vitreous humor. "We describe a young Saudi woman with NF1 who presented with rare and atypical findings of unilateral peripheral retinal ischemia and retinal vascular abnormalities, which led to secondary retinal neovascularization and vitreous hemorrhage." (PMID 39759687, 2024).
vulvar sarcoma (1 paper, 2013). "We report the case of a solitary vulvar sarcoma in a woman with NF1." (PMID 24167749, 2013). "Female genital tract sarcomas are very rare; moreover, no cases of vulvar sarcoma in patients with NF1 have been ever described." (PMID 24167749, 2013).
tumor (1,421 papers, 1994 to 2026). "Due to the broad tumor spectrum associated with NF1, affected individuals are offered receive tailored surveillance, ideally coordinated within specialized centers with NF1 expertise." (PMID 41528496, 2026). "Most of the cell lines are highly enriched for S100B staining, suggesting that very few other cells/cell types are present; those bearing a somatic NF1 mutation in the majority of cells are enriched for the two-hit tumor Schwann cells." (PMID 41564118, 2026). "Complementing optogenetically regulated tumor control, neuronal Nf1 mutations heighten spontaneous action potential discharge rates." (PMID 41583906, 2026). "Neurofibromatosis type 1 (NF1), an autosomal dominant disorder resulting from mutations in the NF1 tumor suppressor gene, predisposes affected individuals to diverse benign and malignant neoplasms." (PMID 41756333, 2026). "Molecular profiling of the tumor revealed a loss-of-function NF1 mutation and a gain-of-function PTPN11 mutation, two convergent alterations in the MAPK pathway." (PMID 41853813, 2026). "This case highlights a possible association between secondary genomic alterations, PRC2-related epigenetic alteration, and aggressive tumor behavior in NF1-associated GIST." (PMID 42176217, 2026). "NF1 is caused by pathogenic variants in the NF1 gene on chromosome 17q11.2, which encodes neurofibromin, which is a large tumor-suppressor protein that negatively regulates RAS signaling and restrains cell proliferation." (PMID 41341331, 2025). "Optic pathway gliomas are other common NF1-associated neoplasms, occurring in up to 20% of pediatric cases." (PMID 40361417, 2025). "Autosomal dominant mutations in the neurofibromin 1 (NF1) gene cause tumor formation and neuronal dysfunction, leading to cognitive, language, and behavioral deficits, with high rates of ASD." (PMID 40605060, 2025). "In this preclinical study, we set out to investigate the impact of tovorafenib alone or in combination with MEK inhibitor pimasertib in adult or pediatric tumor models harboring either an AGK::BRAF fusion or an NF1-LOF mutation." (PMID 40111124, 2025). "The drug negatively affects cell proliferation in NF1-deficient cells, reducing tumour burden and proving particularly effective in decreasing the size of PNs." (PMID 40282482, 2025). "Treatment of HRAS-mutant tumours with tipifarnib over long periods resulted in resistant tumours that harbour a mutation in NF1 and GNAS." (PMID 40332222, 2025). "The epidemiology of NF2-SWN has only been possible to delineate after the separation of NF2-SWN from the much more frequent nerve sheath predisposing tumour condition NF1." (PMID 41160189, 2025). "Consistent with the designation of NF1 as a tumor suppressor gene, in PNF, Schwann cells show loss of function of both NF1 alleles." (PMID 40075752, 2025). "This sustained tumor shrinkage is observed in both benign and malignant tumors associated with different neurofibromatosis subtypes, including NF1, NF2, and schwannomatosis, highlighting the drug’s broad therapeutic potential." (PMID 40725763, 2025). "While VA deterioration or radiologically detectable tumor growth are considered key determinants for treatment initiation both in NF-1-associated and sporadic OPG, previous studies primarily focused on analyzing the impact of tumor volume on VA outcomes." (PMID 40643687, 2025). "Mutations in genes such as EGFR, PDGF Receptor Alpha (PDGFRA), and Neurofibromin 1 (NF1) are considered driver mutations that define distinct clonal populations and contribute to tumor heterogeneity." (PMID 40358199, 2025). "This patient underwent genetic screening after tumor resection, which was unremarkable for all markers associated with NF1." (PMID 40532547, 2025).
tumor (continued). "Recently there has been a shift to targeting tumor-driving mutations besides the mutation in NF1 and its resultant activation of the RAS pathways." (PMID 41374983, 2025). "To understand the potential mechanisms underlying the anti-tumor effects of MSU-42011 in NF1, we used several mouse and human NF1-deficient cell lines to perform in vitro studies." (PMID 40563570, 2025). "cNF development begins with bi-allelic NF1 loss in the Schwann cell (SC) lineage, followed by the recruitment of a complex tumor microenvironment consisting of fibroblasts, immune cells, blood vessels, axons, and a dense extracellular matrix." (PMID 40684195, 2025). "This long-term treatment showed significant benefits in tumor control and quality of life, paving the way for its application in other NF1-associated complications." (PMID 39912006, 2025). "This study not only advances a viable AAV vector for NF1 treatment but also outlines a replicable strategy for vector and payload development in other monogenic and tumor-associated disease manifestations." (PMID 41022755, 2025). "The cells driving the formation of the tumour are Schwann cells that contain variants in the NF-1 gene that disinhibit the local RAS pathway causing cell proliferation, but this cell proliferation is not confined to Schwann cells." (PMID 39254838, 2025). "NF1 is caused by the mutation of a gene on chromosome 17, which hinders the production of the protein neurofibromin, a tumor suppressor that acts on the rat sarcoma (Ras) pathway." (PMID 40270760, 2025). "NF1 is a multi-system disease resulting from dominantly inherited mutations in the NF1 tumor-suppressor gene, which encodes neurofibromin." (PMID 40279245, 2025). "The inhibition of STAT3 has also been shown to suppress tumor growth in both NF1-deficient pNFs and MPNSTs, while also reducing macrophage infiltration, inflammation, and cytokine expression, and enhancing apoptotic cell death in vivo." (PMID 41294711, 2025). "Mutations in NF1 in SCs are the initial tumor-forming event that leads to either complete loss or substantial reduction of neurofibromin function, resulting in hyperactivation of RAS and multiple downstream signaling pathways." (PMID 40940747, 2025). "Co-culture systems or conditioned media are two strategies to study the influence of the tumor microenvironment on NF1-deficient cells." (PMID 41294711, 2025). "In this study, the impact of tovorafenib alone or in combination with MEK inhibitor, pimasertib, was explored in adult or pediatric tumor models harboring BRAF fusions or NF1-LOF mutations." (PMID 40111124, 2025). "The disease is caused by mutations in the NF1 gene, a tumour suppressor gene located on chromosome 17." (PMID 40437318, 2025). "For instance, Nf1 heterozygous microglia promote the proliferation of Nf1-deficient astrocytes via the secretion of hyaluronidase, a critical factor in tumor progression." (PMID 40076738, 2025). "In order to improve the clinical outcome of these patients, a surveillance program to detect NF1-associated neoplasms in adults is highly relevant." (PMID 40282482, 2025). "Here, we describe the generation of a dNF1 null mutant Drosophila cell line using CRISPR and its use in synthetic lethal screens to identify candidate drug targets to specifically kill NF1‐associated tumor cells." (PMID 39129390, 2025). "Accurate modeling of NF1-associated tumors preserving the tumor microenvironment and immune contexture is critical for preclinical drug evaluation." (PMID 41294711, 2025). "Together, these results support the specificity of ctDNA alterations to malignant transformation and the concordance of cfDNA profiles with tumor biology in NF1-associated MPNST." (PMID 41255978, 2025).